SPOP (speckle type BTB/POZ protein)
Diseases named in the same sentence as SPOP in open-access papers (continued):
Sharing a sentence is not in itself a finding about the gene and the disease.
cancer (continued). "LPD5 cancer samples exhibited exactly the reverse pattern of genetic alteration: there was under-repression of ETS and PTEN gene alterations, and over-representation of SPOP and CHD1 alterations." (PMID 32203215, 2020). "While numerous downstream substrates of SPOP have been identified, there is no molecular mechanism or regulator known for wild-type SPOP protein in any cancer." (PMID 33158056, 2020). "To explore whether these cancer-derived SPOP mutants also affects their interaction with HDAC6, we performed GST pull-down assays and found that SPOP mutants including Y87C, F102C, W131G, F133L, or F133V, but not SPOP WT, failed to interact with HDAC6." (PMID 28599312, 2017). "On the other hand, several studies have shown that an SPOP deficiency did not significantly affect cell proliferation according to an MTS and CCK-8 assay, even though SPOP depletion increases cell migration and invasion in cancer." (PMID 39540935, 2024). "Contrastingly, cancer-related SPOP mutants no longer modulated hRpb7 stability." (PMID 37554435, 2023). "Moreover, cancer-derived SPOP mutants failed to decrease endogenous PrLZ protein abundance comparing to SPOP WT, thereby incapable of affecting the half-life and ubiquitination of PrLZ protein." (PMID 35194188, 2022). "For example, miR-145 and miR-543 reduced endogenous SPOP levels in human CRC, BC, CC, HCC and GC cells by directly targeting a conserved putative binding site in the 3′-untranslated regions (3′-UTRs) of SPOP transcripts, promoting the invasion and migration of cancer cells." (PMID 31901237, 2020). "Furthermore, we show here SPOP has substrate specificity and regulates distinguished transcription programs in PCa and CCRC cell lines, suggesting complicated mechanisms exit for SPOP substrate selectivity in different cancers." (PMID 30237511, 2019). "Our findings might imply that SPOP is not a significant prognostic indicator for PFS in cancer patients." (PMID 31577764, 2019). "However, SPOP expression did not affect progression-free survival in cancer patients (high/low: HR = 2.07; 95% CI: 0.16–26.70, P = .578)." (PMID 31577764, 2019). "Notably, compared to SPOP WT, cancer-derived SPOP mutants failed to decrease the protein abundance of endogenous HDAC6 in cells." (PMID 28599312, 2017). "In keeping with these findings, we further found that ectopic expression of SPOP WT, but not cancer-derived mutants, could promote the degradation of HDAC6 in cells in a dose-dependent manner, which largely was due to deficiency in promoting the poly-ubiquitination of HDAC6 in cells." (PMID 28599312, 2017). "Additionally, the association between SPOP overexpression and LNM was positive in patients with clear cell renal cell carcinoma (ccRCC) (OR = 5.26; 95% CI: 1.66–16.68, P = .005) but negative in cancer patients without ccRCC (OR = 0.36; 95% CI: 0.21–0.62, P < .001)." (PMID 31577764, 2019). "In conclusion, this meta-analysis clarified that decreased SPOP expression predicts poor OS in cancer patients, and positively correlates with LNM in cancer patients without ccRCC rather than in cancer patients with ccRCC." (PMID 31577764, 2019). "For this meta-analysis, the overall pooled result including 5 eligible studies did not predict a significant relationship between SPOP expression and LNM in cancers." (PMID 31577764, 2019).
prostate (8 papers, 2015 to 2023). "By establishing a tissue-specific SPOP-F133V overexpressing GEM model, Blattner and colleagues reported that SPOP mutation promotes prostate tumorigenesis through coordinate regulation of PI3K/mTOR and AR signaling." (PMID 36776288, 2023). "Altogether, our findings show the feasibility of exploiting the G3BP1-mediated suppression of SPOP’s ubiquitin ligase function for intervention against prostate tumorigenesis." (PMID 34795264, 2021). "Moreover, several studies on Speckle-type POZ protein (SPOP) further expanded our understanding on the role of LLPS in prostate carcinogenesis." (PMID 35966880, 2022).
infection (5 papers, 2021 to 2024). The state of being infected such as from the introduction of a foreign agent such as serum, vaccine, antigenic substance or organism. "Consequently, we anticipate the development of a mouse model that mimics the infection mechanism observed in humans, which would enable the confirmation of SPOP function in vivo during EV71 infection using SPOP-deficient mice." (PMID 37796126, 2023). "We further utilized the lentivirus infection method to attenuate CHAF1A expressions in SPOP-deleted cells and found that CHAF1A knockdown significantly impaired the malignant features of SPOP-deficient DLBCL." (PMID 35773729, 2022). "Besides, we selected HepG2 and SK-Hep1 cells to construct stable cell lines with SPOP knockdown (Control/sh SPOP#1/sh SPOP#2/sh SPOP#3) and SPOP overexpression (Control/SPOP-OE) by lentiviral infection." (PMID 38340178, 2024). "The results indicated that neither overexpression nor knockdown of SPOP can affect cellular infection with either VSV or HSV." (PMID 37796126, 2023).
adenocarcinoma (4 papers, 2019 to 2025). A common cancer characterized by the presence of malignant glandular cells. "Upon the gain of expression of the SPOP F133V gene, adenocarcinoma that is invasive, poorly differentiated, and highly proliferative is observed due to SPOP mutation-induced AR signaling activation." (PMID 36358740, 2022).
digestive system cancer (1 paper, 2019). A primary or metastatic malignant neoplasm involving any part of the digestive system. "In the subgroup analyses, the adverse prognostic role of decreased SPOP expression remained significant in digestive system cancers, the large sample size group, studies performed in Asian countries and those published between 2015 and 2017." (PMID 31577764, 2019). "The results showed that low SPOP expression was significantly related to poor overall survival (high/low: HR = 0.55; 95% CI: 0.38–0.79, P = .001), especially for digestive system cancers (high/low: HR = 0.46; 95% CI: 0.27–0.78, P = .003)." (PMID 31577764, 2019).
neurodevelopmental disorder (1 paper, 2022). A behavioral and cognitive disorder with onset during the developmental period that involves impaired or aberrant development of intellectual, motor, or social functions. "Nabais Sa‐de Vries syndrome (NSDVS) is a newly identified neurodevelopmental disorder (NDD), characterized by mutations in the SPOP gene, which encodes the speckle‐type BTB/POZ protein." (PMID 36259278, 2022).
SPOP also shares sentences with these, for which no sentence is quoted: thyroid cancer (3 papers); glioblastoma (2); malignant thyroid tumors (2); medulloblastoma (2); uterine corpus endometrial carcinoma (2); acinar adenocarcinomas (1); acral melanoma (1); Alzheimer disease (1); amyotrophic lateral sclerosis (1); androgen insensitivity syndrome (1); bone metastasis (1); bone osteosarcoma (1); carcinosarcoma (1); choriocarcinoma (1); colon adenocarcinoma (1); embryonal cancer (1); hematologic malignancies (1); hematopoietic neoplasms (1); neuroblastoma (1); neurodegenerative disease (1); pancreatic endocrine tumours (1); papillary thyroid cancers (1); partial androgen insensitivity syndrome (1); pediatric cancers (1); respiratory tract tumor (1); squamous cell carcinoma (1); undifferentiated carcinoma (1); uterine serous carcinoma (1); uveal melanoma (1).